ENSG00000285854 (novel transcript)
Gene: Protein-coding gene on chromosome 12 (21,536,203 to 21,657,798, reverse strand). Ensembl gene ENSG00000285854.
Genetic constraint (gnomAD): Missense variants: 238 observed, 275.92 expected, observed/expected ratio (o/e) 0.86, 90% interval 0.77 to 0.96. Synonymous variants: 80 observed, 92.89 expected, observed/expected ratio (o/e) 0.86, 90% interval 0.72 to 1.04.